MET (MET proto-oncogene, receptor tyrosine kinase)
Diseases named in the same sentence as MET in open-access papers (continued):
Sharing a sentence is not in itself a finding about the gene and the disease.
tumor (continued). "The CD44v6 isoform is required for c-MET activation by hepatocyte growth factor (HGF, or scatter factor) and as such plays an essential role in triggering EMT at the invasive front where tumor cells are exposed to these TME-secreted factors." (PMID 36346211, 2022). "Further, SNX5422 also induced the degradation of MET and inhibits key downstream mediators of MET activity including activated forms of MET(Y1234/1235), AKT (Ser473) and ERK (Thr202/Tyr 204) in tumor-bearing xenografts (n = 3, each group) as demonstrated by western blotting." (PMID 35754026, 2022). "The last strategy can have an important therapeutic effect on the generation of a strong inflammatory anti-cancer response in the tumour tissue, which can also target a c-MET non-expressing cancer cells population." (PMID 36498560, 2022). "The investigators hypothesized that simultaneous targeting of both MET and VEGFR2 by cabozantinib might combine antivascular and anti-tumor activity." (PMID 36428705, 2022). "In addition, HGF, MET amplification, and EGFR T790M lead to the upregulation of PD-L1 expression in NSCLC and promote immune escape by tumor cells through different mechanisms mediated by the PI3K-Akt, MAPK, and NF-κB pathways." (PMID 35840984, 2022). "To validate their expressions, we used the UALCAN online bioinformatics tool with default settings, which showed that mRNA levels of DPP4/CTNNB1/MET were higher in THCA tumor tissues compared with adjacent normal tissues." (PMID 35205190, 2022). "Tumor samples (solid tumors including CNS tumors) were analyzed for c-MET expression by IHC, and the majority of samples [81% (26/32)] were found to have undetectable levels of c-MET." (PMID 36034555, 2022). "Small molecule inhibition of c-MET in vitro in MB cell lines led to decreased proliferation, motility, and anchorage-independent growth, and treatment with an oral c-MET inhibitor (crizotinib) in vivo inhibited growth of subcutaneous MB tumor xenografts." (PMID 36034555, 2022). "In order to evaluate whether MET levels are modulated after NOTCH signaling inhibition, we silenced NOTCH1 and NOTCH3, the two NOTCH receptors hyper-activated in our cell tumor context, in two FP-RMS (RH30 and RH4) and two FN-RMS (RD and JR1) cell lines." (PMID 35574376, 2022). "From a total amount of 87 tumor lesions defined by CT criteria, 18/87 (20.7%) tumor lesions were visually c-MET-negative (sensitivity 82.9%)." (PMID 34708249, 2022). "Our study found that MeT enhanced expression of MHC class I genes and increased T cell activity, suggesting that this regulator of viral mimicry could increase tumour cell immunogenicity, which is critical to improve response to ICIs." (PMID 36923279, 2022). "As EPP suppressed the STAT3 and MET/AKT pathways, which stimulate tumor growth and confer EGFR TKI resistance, EPP could be applied not only to EGFR TKI-naïve or -sensitive NSCLC, but also to EGFR TKI-resistant NSCLC." (PMID 35408753, 2022). "Meanwhile, some scientists have proposed that the anti-tumor mechanism of Tetrastigma hemsleyanum may include calcium signaling pathway, PI3K/AKT/mTOR signaling pathway and CDK6 and MET genes." (PMID 36389762, 2022). "As stated in Methods, all patients with available tumor tissue sample were screened for mutations in the entire series of additional candidate genes (KRAS, ALK, BRAF, MET) regardless of the positive or negative result of the EGFR mutation testing." (PMID 35012520, 2022). "Moreover, it is known a direct action of NRF2 on proteins involved in chemoresistance such as AKR1C1-3, ABCF2, SLC40A1, as well as on the modulation of important growth factor receptors, such as c-MET, ErbB2 and EGFR regulating tumour growth." (PMID 35453348, 2022). "Cabozantinib is an inhibitor of VEGFR2, MET, and RET that also binds to the ATP-binding site of RTKs, thereby inhibiting autophosphorylation of RTKs, which leads to tumor hypoxia and apoptosis and suppresses metastasis, angiogenesis, and tumor growth." (PMID 36209184, 2022).
tumor (continued). "The number of CSCs with the EpCAM+CD44+MET+CD47+ phenotype increased with tumour progression, while no significant changes were found in the number of CSCs representing the main population of tumour cells." (PMID 35563449, 2022). "Unfortunately, little in vitro data is available for the effects of capmatinib on head and neck cell lines; however, it is known to be a potent inhibitor of c-MET in a kinase assay (enzymatic IC50 0.13 nM) and proliferation of other tumor lines (cell IC50 1.2–12.4 nM)." (PMID 35081970, 2022). "The European Organization for Research and Treatment of Cancer (EORTC) “CREATE” trial was designed as a multi-center multi-tumor trial to evaluate crizotinib in a range of cancer types known to harbor alterations in the targets of crizotinib (ALK, MET, and ROS-1)." (PMID 36034555, 2022). "Since recent studies have shown the efficacy and tolerance of sitagliptin as cancer therapeutic, it would be interesting to further investigate its activities as a target for DPP4/CTNNB1/MET signaling pathways in THCA, both in vitro and in vitro in tumor-bearing mice." (PMID 35205190, 2022). "Recently, MET proto-oncogene receptor tyrosine kinase (MET)-derived circRNA (circMET) (hsa_circ_0082002, a 1214 bp circRNA) was found to exhibit the greatest overexpression in HCC tissues compared to non-tumor liver tissues among the circRNAs derived from the chromosome 7q21–7q31 region." (PMID 35053615, 2022). "Significant regulation of 8 out of 14 phosphosites (termed ‘oncogene addiction phosphorylation signature’, OAPS) that are modulated by METi in MET-addicted systems was detected also in EGFR-, ALK- and BRAF-addicted cellular tumor models following EGFR, ALK and BRAF targeting, respectively." (PMID 36494469, 2022). "Strikingly, a recent study by de Vries and coworkers demonstrated an at least 70% expression of c-MET in 14 out of 15 men with PeCa and proved the feasibility of fluorescence imaging with the c-MET targeting tracer EMI-137 for intraoperative tumor visualization using a cyanine-5 fluorescence camera." (PMID 35406455, 2022). "In a phase 2 study the addition of the specific MET inhibitor tivantinib to cetuximab allowed only 10% of MET-high, KRAS-wt mCRC patients to achieve objective response, even though in a difficult-to-treat setting (tumor progression on cetuximab or panitumumab after a first-line chemotherapy)." (PMID 35582524, 2022). "Interestingly, MET induces MAPK re-activation in all tested HNSCC models, and blocking of MAPK with a MET inhibitor re-sensitized the HGF-stimulated tumor cells to cetuximab." (PMID 33596979, 2021). "In this study, we systematically analyzed 11 different cancers, including expression correlation, immune infiltration, tumor diagnosis and survival prognosis from HGF/c-MET pathway and immune regulation, two biological mechanisms that have received extensive attention in cancer analysis." (PMID 34261467, 2021). "c-MET and EGFR regulate the synthesis and secretion of several angiogenic growth factors, including basic fibroblast growth factor (bFGF), vascular endothelial growth factor (VEGF), and interleukin (IL)-8, in tumor cells." (PMID 34512327, 2021). "In cancer models, it was proven that HGF/c-MET is responsible for the resistance to anti-VEGF therapy with sunitinib (VEGFR and PDGFR RTKi), while the concomitant exposure to HGF/c-MET inhibitors and sunitinib abrogated angiogenesis and tumor growth." (PMID 33916438, 2021). "In conclusion, although osimertinib combined with crizotinib showed dramatic tumor shrinkage both in primary tumor and bone metastasis in EGFR T790M-mutant NSCLC patients with MET amplification, more studies should be performed to confirm the clinical benefit in PFS and overall survival." (PMID 34397683, 2021). "Therefore, to achieve a successful tumor diagnosis or prognosis assessment more comprehensively, systematic integration of the HGF/c-MET pathway and immune-related pathways are needed for further analysis." (PMID 34261467, 2021).
tumor (continued). "To investigate how c-MET may determine tumor radiosensitivity in patients with HNSCC, we correlated the MET gene expression with occurrence of canonical pathways in silico within the TCGA dataset (n = 473)." (PMID 33919702, 2021). "A total of 122 patients were eligible in this study, of which tumor sections from 116 patients were assessed in terms of MET staining, but not for 6 patients due to insufficient number of tumor cells in the prepared sections." (PMID 34557411, 2021). "Consistently, MET expression was positively correlated with XIST but negatively with miR-34a levels in tumor specimens." (PMID 33763422, 2021). "Overall, these observations indicated that LECT2 might antagonize FOXM1 signaling via targeting HGF/MET, which affects multiple biological processes and slow down PDAC tumor formation and metastasis." (PMID 33937262, 2021). "Consistent with our previous observations, the MET-positive group showed MET overexpression by IHC only in epithelioid tumor cells, i.e., in EMMs and in the epithelioid but not sarcomatoid component of BMMs." (PMID 34884673, 2021). "In the study of EMD 1214063 and EMD 1204831, both candidates triggered tumor regression in a dose-related fashion by inhibiting c-MET phosphorylation, regardless of HGF-dependent or HGF-independent activation." (PMID 35087755, 2021). "In vitro 4T1 tumor cell growth was also unaffected by 48 h treatment with OMO-1 compared to DMSO control as determined by neutral red uptake assay, which is to be expected from a non-c-MET addicted cell line." (PMID 33731699, 2021). "Although MET N375S did not have impacts on cell proliferation, an increase in tumor size and weight was observed in tumors harboring the MET N375S mutation." (PMID 34439385, 2021). "Since PSCs, like most fibroblasts, do not express MET, the inhibitory activity of the Combo treatment is an indirect effect exerted by tumor-secreted mediators able to transmit the signal from MET-expressing cancer cells to stromal cells." (PMID 34298732, 2021). "Thus, our in vivo results showed that inhibition of c-MET fortified TMZ cytotoxicity in the hypoxic environment, significantly mitigating tumor xenograft growth." (PMID 33859738, 2021). "It is therefore reasonable to conclude that c-MET/EGFR are important biomarker signatures of tumorigenesis, tumor immune invasion, and poor prognoses, and thus can serve as attractive targets for the development of immune/chemotherapeutic strategies against CRC." (PMID 34512327, 2021). "MET RNA‐ISH and c‐MET IHC protein expression was found to demonstrate a moderate‐positive relationship in the absence of genetic aberration influencing relative c‐MET expressed from the tumour." (PMID 34428346, 2021). "We systematically analyzed 11 different cancers, including expression correlation, immune infiltration, tumor diagnosis and survival prognosis from HGF/c-MET pathway and immune regulation, two biological mechanisms having received extensive attention in cancer analysis." (PMID 34261467, 2021). "Several amplifications, both in HER2 and MET, were exclusively identified by ISH, usually owing to low tumor cell percentage, low amplification (fewer copies), or the amplification being present only in part of the tumor cells (clonal heterogeneity)." (PMID 34849493, 2021). "Together, these data suggest that cabozantinib inhibits SCNPC tumor growth in vivo irrespective of tumor MET and RET status." (PMID 33471819, 2021).
tumor (continued). "Given that RTK coactivation plays an important role in tumor response to RTK-targeted therapy, we sought to use molecular imaging to understand and visualize the interplay between MET, EGFR, and HER2 receptor dynamics in our PDX model, which expresses all 3 receptors." (PMID 32646879, 2021). "Of the 71 patients who had paired pre- and post-treatment tumor tissues, 28 patients (39%) were initially positive for MET expression, and 43 (61%) were negative." (PMID 34557411, 2021). "Since aberrant c-MET function plays an important role in the metastatic capacity, we examined the in vivo effect of the c-MET inhibitor SU11274 on primary tumor proliferation and liver colonization ability of the cetuximab resistant PE/CA-PJ15 and the cetuximab sensitive PJ41 HNSCC cells." (PMID 34257586, 2021). "Tumor masses from HCC PDX mice treated with omacetaxine and negative control were utilized to prepare frozen sections, which were then stained for the c-Myc, MET, β-catenin, XIAP, and cyclin D1." (PMID 34003798, 2021). "Although c-MET activation is transient during physiological events, c-MET signaling may be constitutively active during tumor onset and progression." (PMID 34261467, 2021). "Additionally, the assay incorporates whole transcriptome sequencing of the tumor sample that allows for the detection of gene fusions and select special transcripts, including AR-V7, EGFR vIII, EGFRvIV, and MET exon 14 skipping events." (PMID 33889297, 2021). "Telisotuzumab vedotin (formerly ABBV‐399) is an antibody‐drug conjugate targeting c‐Met–overexpressing tumor cells, irrespective of MET gene amplification status." (PMID 33675179, 2021). "MET mRNA showed a 3-fold increase in the tumor vs non-tumor normal tissue (3.02±2.16), while the expression of ERBB2 seems no change (0.93±0.69)." (PMID 34335943, 2021). "The binding of HGF and c-MET triggers several downstream signaling pathways such as phosphoinositide 3-kinase/threonine-protein kinase (PI3K/AKT) pathway, wingless-related integration site (Wnt) pathway, and other tumor-related functions." (PMID 34261467, 2021). "This study was designed to determine whether increased MET and RET expression and activity in SCNPC could be blocked by cabozantinib to inhibit tumor growth." (PMID 33471819, 2021). "Because HER2, IGF1R, MET and NTRK2 are also present in tumor-derived exosomes that play important roles in tumor progression, we aimed to investigate whether RAB31 control these RTKs entry into CD63-positive MVEs." (PMID 32958903, 2021). "Upon binding to its receptor MET, HGF can promote the invasion and metastasis of tumor cells." (PMID 33732214, 2021). "Pre-clinical and clinical evidence suggests that HGF/MET inhibitors display cytostatic rather than cytotoxic activity on tumor cells." (PMID 34200749, 2021). "In a third of patients assessed for MET expression analysis, there was a lack of agreement in dichotomised low and high groups representing MET RNA‐ISH and c‐MET IHC protein expression, with nonconcordance demonstrated in 27.91% of tumours assessed." (PMID 34428346, 2021). "This chromosomal region harbors several protein-coding genes that have been validated as oncogenes in solid tumors, such as MET, CAV (caveolin) and WNT229-31, which may account for its tumor-promoting role in ICC." (PMID 33754015, 2021). "However, carbotinib has fairly multiple anti-tumor targets, including VEGFR2, MET, PDGFRβ, and so on." (PMID 33892656, 2021). "We found that MET expression was significantly higher in HCC tumor tissues than in 50 normal tissue samples, and a positive correlation between the expression of PLAGL2 and MET was observed in 15‐paried HCC tumor tissues (r = 0.5730, p < 0.01)." (PMID 34586726, 2021). "For example, VEGF can inhibit the c-MET pathway; thus, anti-VEGF drugs may block this pathway and promote tumor development." (PMID 34568049, 2021).
tumor (continued). "The property of the immune system to discriminate tumor-derived antigens as non-self and to be activated to eliminate cancer cells indicates a connection of tumor immunotherapy with MET-targeted therapy." (PMID 34479614, 2021). "ARQ 197 (tivantinib), a non-ATP-competitive inhibitor of c-MET, decreased tumor growth in a HT29 xenograft mouse model." (PMID 33466394, 2021). "The activity of this agent was assessed in MET-positive and MET-negative cases, where the MET status was defined by fluorescence in situ hybridization (FISH), detecting EWSR1 rearrangements in at least 15% of the tumor cells." (PMID 34885165, 2021). "In contrast to NSCLC, we observed no significant heterogeneity of MET-protein expression in the MMs (i.e., cases with upregulated expression showed that in the vast majority of tumor cells)." (PMID 34884673, 2021). "For instance, in an in vitro experiment in which human umbilical vein endothelial cells (HUVECs) have been used to mimic the tumor microenvironment GDNF was able to stimulate the hepatic growth factor (HGF) production and consequently the phosphorylation of its main receptor MET." (PMID 33806299, 2021). "Low numbers of CXCR4+MET+CD44+ cells initiated tumor growth, while negative samples, with one exception, failed to do so." (PMID 32066735, 2020). "Additionally, numerous targets of expressions which were observed in carcinogenesis and tumor progression were reported to be regulated by miR-34a, such as CD44, BCL2, NOTCH1, CDK4/6, MET, MYC, and many other molecules." (PMID 32391256, 2020). "Acquired resistance is classified as the progression of tumor after initial tumor regression during the therapy, which is often driven by the development of other pathways stimulating angiogenesis, such as AXL, MET, and PDGF/PDGFR, and thus the escape of cancer cells from VEGF/VEGFR blockade." (PMID 33510766, 2020). "Thus, co‐treatment of GC (HS746T and AGS, with higher and lower expression of BRCA1/2 and c‐MET, respectively) cell lines with PARP and c‐MET inhibitors reduces cell viability through apoptosis and attenuated tumour growth in xenograft models." (PMID 32686903, 2020). "Additionally, the coordination of tumor metabolism and autophagy are critical for the resistance to HGF/MET-targeted therapy." (PMID 32435640, 2020). "In addition, LY2801653 also inhibited the in vivo growth of MET and AXL‐independent cells at higher but clinically relevant doses through decreasing M2 macrophages in the tumor microenvironment." (PMID 34766112, 2020). "In pancreatic cancer, HSPG-mediated activation of HGF/c-MET signaling induces proliferation and migration of tumor cells through the activation of ERK1/2 but not the AKT pathway." (PMID 32916872, 2020). "Molecular analyses for all patients were negative for EGFR and ALK aberrations, one patient had a MET‐amplified tumor and two patients had high TMB." (PMID 32548905, 2020). "Other tumor biomarkers have been proposed such as osteopontin (OPN), vascular endothelial growth factor (VEGF), angiopoietin 2 (ANG-2), Golgi protein 73 (Gp-73), insulin growth factor-1 (IGF-1), hepatic growth factor (HGF), Glypican-3 and c-MET among others." (PMID 32492896, 2020). "Several reports have shown that some miRNAs (such as miR-449b and miRNA-3666) act as tumor suppressors that inhibit TC growth and reduce apoptosis by decreasing the levels of MET protein rather than its transcription." (PMID 32083078, 2020).